CLCA4 (chloride channel accessory 4)
Description:
May be involved in mediating calcium-activated chloride conductance.
Synonyms: CaCC2; CaCC
Tractability: Small molecule: it belongs to a druggable protein family. Antibody: its Gene Ontology location is reachable by antibodies, with high confidence; UniProt places it where antibodies can reach, with medium confidence; UniProt predicts a signal peptide or a membrane-spanning region; the Human Protein Atlas places it where antibodies can reach.
Gene: Protein-coding gene on chromosome 1 (86,547,076 to 86,580,758, forward strand). Ensembl gene ENSG00000016602.
Subcellular location: Cell membrane; Apical cell membrane; Secreted
Subcellular location (Human Protein Atlas): Plasma membrane; Aggresome; Nucleoplasm
Pathways (Reactome):
Transport of small molecules: Stimuli-sensing channels
Gene Ontology:
Molecular function: chloride channel activity; intracellularly calcium-gated chloride channel activity; metalloendopeptidase activity
Biological process: monoatomic ion transmembrane transport; chloride transmembrane transport; chloride transport
Cellular component: plasma membrane; apical plasma membrane; extracellular region
Genetic constraint (gnomAD): Loss-of-function variants: 50 observed, 58.68 expected, observed/expected ratio (o/e) 0.85, 90% interval 0.68 to 1.08. The upper end of that interval is the gene's LOEUF score, 1.08, which puts it in group 4 of 6, group 1 being the genes least tolerant of losing a copy. Missense variants: 923 observed, 971.45 expected, observed/expected ratio (o/e) 0.95, 90% interval 0.9 to 1. Synonymous variants: 306 observed, 337.76 expected, observed/expected ratio (o/e) 0.91, 90% interval 0.82 to 1.
Homologues: Orthologues: chimpanzee CLCA4 (99% identical), macaque CLCA4 (90% identical), dog CLCA4 (78% identical), mouse Clca4b (71% identical), mouse Clca4a (70% identical), rat Clca4 (69% identical). Paralogues in human: CLCA1 (61% identical), CLCA2 (43% identical).
Diseases named in the same sentence as CLCA4 in open-access papers:
CLCA4 is named in the same sentence as 33 diseases in open-access papers, as found by Europe PMC text mining. Sharing a sentence is not in itself a finding about the gene and the disease. The quoted sentences say what the papers report.
breast carcinoma (10 papers, 2013 to 2022). "Previous studies showed that knockdown of CLCA4 expression caused downregulation of E-cadherin and upregulated the expression of N-cadherin and vimentin in breast cancer cells." (PMID 30312171, 2018). "In addition, low CLCA4 expression was associated with overall survival in patients with various tumors, including CC, head and neck cancer, gastric cancer, and breast cancer." (PMID 35479956, 2022). "Moreover, CLCA4 was reduced in colorectal cancer, and CLCA4 expression was associated with the overall survival rate of patients with breast cancer, stomach cancer, colorectal cancer, and head and neck cancer." (PMID 34194494, 2021). "Moreover, CLCA4 down-expression was associated with poor relapse-free survival in basal and luminal B breast cancers." (PMID 30312171, 2018). "Recently, CLCA4 was found to be aberrantly expressed in breast cancer, and its ectopic expression inhibited tumour cell growth as well as the epithelial to mesenchymal transition." (PMID 29190973, 2017). "Accordingly, patients with low CFTR, CLCA2 or CLCA4 mRNA abundance in breast cancer specimens have higher odds of developing metastases and a decreased relapse-free survival (green)." (PMID 27618016, 2016). "We found that CLCA4 was similarly downregulated in breast cancer, that its ectopic expression inhibited breast cancer cell proliferation, and that CLCA4 knockdown induced EMT in mammary epithelial cells." (PMID 24386311, 2013). "We show here that another member of the CLCA gene family, CLCA4, is expressed in mammary epithelial cells and is similarly downregulated in breast tumors and in breast cancer cell lines." (PMID 24386311, 2013). "Clinically, low expression of CLCA4 signaled lower relapse-free survival in basal and luminal B breast cancers." (PMID 24386311, 2013). "Studies have shown that CLCA4 can inhibit tumor differentiation in breast cancer." (PMID 32462020, 2020). "Clinical data analysis showed that patients with breast cancer with low expression of CLCA4 had lower recurrence-free survival rate, suggesting that it may serve as a diagnostic and therapeutic target." (PMID 32797167, 2020). "Similarly, it has been reported that CLCA4 is downregulated and promotes EMT in breast cancer, which indicates a tumor-suppression function for CLCA4." (PMID 28974231, 2017). "We found loss of CLCA4 indicated lower relapse-free survival in basal breast cancers that were negative for both estrogen receptor and progesterone receptor and lymph-node positive." (PMID 24386311, 2013). "To confirm previous observations and determine whether CLCA4 was downregulated in breast cancer as reported for colon cancer, we compared CLCA4 expression patterns in a curated database, The Cancer Genome Atlas (TCGA), using Oncomine." (PMID 24386311, 2013). "We tested whether ectopic expression of CLCA4 inhibited tumor cell proliferation by lentivirally transducing Flag-tagged CLCA4 into MCF7 breast cancer cells and assessing the ability of the cells to form colonies." (PMID 24386311, 2013). "However, CLCA4 did confer a statistically significant relapse-free survival advantage to patients with Luminal B breast cancers, a subtype that is generally low in estrogen and progesterone receptors and prone to relapse." (PMID 24386311, 2013).
colorectal cancer (10 papers, 2016 to 2025). A primary or metastatic malignant neoplasm that affects the colon or rectum. "Our data showed that CLCA1 and CLCA4 were significantly downregulated in colorectal cancer compared with normal tissues." (PMID 35693937, 2022). "Previous studies have shown that the increase of CLCA1 and CLCA4 levels in tumor tissue is related to the excellent prognosis of colorectal cancer patients, consistent with our survival analysis." (PMID 35693937, 2022). "The in vitro experiments in colorectal cancer show that overexpression of CLCA4 can inhibit cancer cell migration and invasion by suppressing epithelial-mesenchymal transition (EMT) via PI3K/ATK signaling." (PMID 32462020, 2020). "The down expression of five genes (SLC26A3, GUCA2A, CLCA4, CLCA1, and AQP8) was significantly associated with poor overall survival in colorectal cancer adenocarcinoma patients, and patients with lower expression levels of CLCA1 had poorer disease-free survival rates." (PMID 35693937, 2022). "CLCA4, at the time misidentified as CLCA2, was found to be downregulated in colorectal cancer (CRC), which has been confirmed by several other studies." (PMID 40220130, 2025). "In this study, we discovered that decreased CLCA4 expression was evident in CD133+CD44+ colorectal CSCs and chemoresistant colorectal cancer (CRC) cells." (PMID 41674659, 2025). "Furthermore, CLCA4 might be a target gene for primary colorectal cancer." (PMID 34194494, 2021). "CLCA4 was found to repress cell migrated and invasive abilities by inhibiting the EMT pathway through the PI3K/AKT pathway in colorectal cancer." (PMID 34194494, 2021). "CLCA4, a widely recognized tumour suppressor gene, is considered an inhibitor of invasion, migration and EMT in hepatocellular carcinoma and colorectal cancer." (PMID 34663338, 2021). "Yang found that patients with colorectal cancer CRC had low expression of CLCA1 and CLCA4, and further experiments confirmed that CLCA1 is involved in tumor proliferation and invasion." (PMID 32797167, 2020).
bladder cancer (8 papers, 2017 to 2022). "On the contrary, loss of CLCA4 expression was observed in breast and bladder cancer that facilitated tumor cells growth and metastasis by the way of EMT." (PMID 30312171, 2018). "We demonstrated that CLCA4, whose low expression associates with tumor aggressiveness and unfavorable clinical survival, promoted bladder cancer cell proliferation and metastasis via the PI3K/AKT pathway." (PMID 29190973, 2017). "Multivariable Cox regression analyses revealed that low CLCA4 expression was a risk factor for the overall and recurrent-free survival of bladder cancer patients (P=0.001 and P=0.019, respectively)." (PMID 29190973, 2017). "In bladder cancer and hepatocellular carcinoma, tumor cell proliferation and migration are inhibited by CLCA4 through the PI3K/AKT signalling pathway." (PMID 35300114, 2022). "Studies have shown that CLCA4 inhibits cell proliferation and metastasis in bladder cancer and liver cancer via the PI3K/AKT signaling pathway." (PMID 36532007, 2022). "Low CLCA4 expression was correlated with larger tumor size, advanced tumor stage, and poor prognosis in patients with bladder cancer." (PMID 30312171, 2018). "Taken together, in vivo studies confirmed that depressed expression of CLCA4 promotes tumorigenicity in bladder cancer cells." (PMID 29190973, 2017). "Downregulation of CLCA4 augmented the growth and invasive abilities of bladder cancer cells, while overexpression of CLCA4 reduced these effects via regulating the PI3K/AKT signaling." (PMID 29190973, 2017). "The results implied that CLCA4 suppresses bladder cancer cell proliferation through the PI3K/AKT signaling pathway." (PMID 29190973, 2017). "Our results provide new insights into the mechanism of CLCA4 deregulation in enhancing development of bladder cancer." (PMID 29190973, 2017). "Clinical analysis unraveled that CLCA4 downregulation in bladder cancer was correlated with poor prognosis of patients with bladder cancer." (PMID 29190973, 2017). "To investigate the function of CLCA4 on the tumorigenicity of bladder cancer cells, we performed anchorage-independent growth assay." (PMID 29190973, 2017). "In conclusion, the present study indicated a inverse correlation between CLCA4 expression and the clinical prognosis of bladder cancer patients." (PMID 29190973, 2017). "Overexpression of CLCA4 profoundly attenuated the proliferation, growth, migratory and invasive capabilities of bladder cancer cells, whereas CLCA4 knockdown had the opposite effect." (PMID 29190973, 2017). "In order to explore the clinical significance of CLCA4 in bladder cancer, we analyzed the CLCA4 expression pattern in 196 bladder cancer specimens by real-time PCR." (PMID 29190973, 2017). "We then evaluated the role of CLCA4 on the bladder cancer cell proliferation in established stable CLCA4-overexpressing and CLCA4-knocking down EJ and T24 cells." (PMID 29190973, 2017). "Down-regulation of N-cadherin, vimentin, fibronectin, Zeb1, Twist, and Snail and up-regulation of E-cadherin were observed in CLCA4 overexpressed bladder cancer cells." (PMID 29190973, 2017). "Downregulation of CLCA4 augmented bladder cancer growth and metastasis in vitro and in vivo, which was assumed to be acted by activation PI3K/AKT signaling." (PMID 29190973, 2017). "Low CLCA4 expression was correlated with larger tumor size, advanced tumor stage, and poor prognosis in bladder carcinoma patients." (PMID 29190973, 2017). "Further analysis revealed that CLCA4 may be involved in the proliferation and invasion of bladder cancer through PI3K/AKT signal transduction, suggesting that CLCA4 may be a target for diagnosis and treatment." (PMID 32797167, 2020). "Hu found that CLCA4 was low expressed in bladder cancer tissues." (PMID 32797167, 2020). "To investigate whether CLCA4 expression is correlated with bladder cancer development and progression, we first analyzed CLCA4 expression in bladder cancer cell lines and tissues." (PMID 29190973, 2017).
bladder cancer (continued). "This study suggests that CLCA4 may represent a promising prognostic biomarker for bladder cancer and provides a possible mechanism for bladder cancer growth and invasion." (PMID 29190973, 2017). "In this study, we found that CLCA4 might play a crucial role in the tumorigenesis and progression of bladder cancer." (PMID 29190973, 2017). "Remarkably, our study showed that CLCA4 expression was remarkably depressed, and that down-regulation of CLCA4 significantly promoted, while overexpression of CLCA4 profoundly suppressed bladder cancer cell proliferation, colony formation, invasion, and migration." (PMID 29190973, 2017). "Together with other published data, our results showed that CLCA4 might be exploited as a target for potential clinic treatments of patients with bladder cancer." (PMID 29190973, 2017). "In this study, we examined the role and mechanism of CLCA4 in human bladder cancer." (PMID 29190973, 2017). "In addition, both western blot (WB) and real-time PCR analyses showed that CLCA4 was profoundly down-regulated in all 7 bladder cancer cell lines compared with NBUCs and normal urothelial cells." (PMID 29190973, 2017). "In order to determine whether CLCA4 inhibited the growth capacity of bladder cancer cells, we further explored the biological significance of CLCA4 using Gene Set Enrichment Analysis (GSEA) based on mRNA expression data from the TCGA." (PMID 29190973, 2017). "Moreover, we analyzed mRNA microarray data from GSE13507 database, and surprisingly found the mRNA expression of CLCA4 was drastically decreased in the bladder cancer tissues (P<0.001)." (PMID 29190973, 2017). "We next examined the role of CLCA4 in the migration and invasion of bladder cancer cells." (PMID 29190973, 2017). "Calcium activated chloride channel A4 (CLCA4), a tumor suppressor, was shown to contribute to the progression of several human cancers, while its role in bladder carcinoma remains unclear." (PMID 29190973, 2017). "Furthermore, we examined the role of CLCA4 in the tumorigenicity of bladder cancer cells in vivo." (PMID 29190973, 2017). "Additionally, CLCA4 could mediate the migration and invasion of bladder cancer cells by regulating epithelial-mesenchymal transition and PI3K/Akt activation." (PMID 29190973, 2017). "Therefore, CLCA4 might be exploited as a target for potential anti-cancer treatment of bladder cancer." (PMID 29190973, 2017). "CLCA4 was reported to inhibited cell multiplication and metastasis by inhibiting the PI3K/AKT signaling pathway in bladder cancer." (PMID 34194494, 2021). "Mechanistically, CLCA4 is involved in PI3K/AKT signaling and its downstream molecules can promote bladder cancer cell proliferation." (PMID 29190973, 2017). "In this study, we report that inhibition of CLCA4 activated PI3K/AKT signaling pathway and elevated the expression of various AKT downstream genes that specifically regulate cell proliferation, migration, apoptosis, and angiogenesis in bladder cancer." (PMID 29190973, 2017). "In this study, we showed CLCA4 expression was down-regulated in bladder carcinoma tissues and cells compared to adjacent non-tumor tissues and normal urothelial cells." (PMID 29190973, 2017). "Additionally, western blot analysis showed that CLCA4 expression was markedly lower in bladder cancer than that in adjacent non-tumor tissues." (PMID 29190973, 2017). "However, the biological relationship of CLCA4 and PI3K/Akt signaling in bladder cancer progression remains unclear." (PMID 29190973, 2017). "Unlike their results, our study showed that CLCA4 could be a potential predictor for both overall and recurrent-free survival in bladder cancer patients." (PMID 29190973, 2017).
hepatocellular carcinoma (6 papers, 2018 to 2022). A malignant tumor that arises from hepatocytes. "Calcium-activated chloride channel 4 (CLCA4) was reported to be a tumor inhibitor in hepatocellular carcinoma." (PMID 34194494, 2021). "Calcium activated Chloride Channel A4 (CLCA4), as a tumor suppressor, was reported to contribute to the progression of several malignant tumors, yet little is known about the significance of CLCA4 in invasion and prognosis of hepatocellular carcinoma (HCC)." (PMID 30312171, 2018). "In line with our findings, CLCA4 was found to block cell migration and cell invasion by inhibiting the EMT pathway through the PI3K/ATK pathway in hepatocellular carcinoma." (PMID 34194494, 2021). "Liu found that CLCA4 may inhibit epithelial–mesenchymal transition (EMT) by affecting PI3K/ATK phosphorylation, thereby inhibiting cell migration and invasion of hepatoma cells." (PMID 32797167, 2020).
cystic fibrosis (4 papers, 2014 to 2024). Autosomal recessive disorder caused by pathogenic variants in the CFTR gene (cystic fibrosis transmembrane conductance regulator), which encodes a chloride and bicarbonate channel expressed in epithelial cells, and follow the diagnosis criteria. "CLCA4 was also found to be highly expressed in the human colon and esophagus, and variants of CLCA4 were associated with cystic fibrosis, an inherited disorder that severely damages the lungs and digestive system." (PMID 34488647, 2021). "TMEM16B has been linked to transepithelial fluid transport, smooth muscle contraction, and neuronal excitability, and reduced CLCA4 expression has been observed in diseases hallmarked by disrupted transepithelial secretion, such as cystic fibrosis and Crohn’s disease." (PMID 38825009, 2024). "The human CLCA4 (chloride channel regulator, calcium-activated) modulates the intestinal phenotype of cystic fibrosis patients via an as yet unknown pathway." (PMID 26474299, 2015). "Mutations in CLCA4 can cause cystic fibrosis not being present in the patient." (PMID 24972929, 2014).
colon cancer (2 papers, 2013 to 2022). "A study has shown decreased expression of CLCA4 in colon cancer, which was associated with the development and progression of colon cancer." (PMID 36532007, 2022). "CLCA4 and CLCA1 are both expressed at highest levels in colon, and both are dramatically downregulated in colon cancer." (PMID 24386311, 2013). "In accordance with Bustin, CLCA4 was downregulated in all colon tumor samples relative to normal." (PMID 24386311, 2013).
inflammatory bowel disease (2 papers, 2016 to 2025). A spectrum of small and large bowel inflammatory diseases of unknown etiology. "For genes encoding transcellular transporters, we found a very significant increase in the expression levels of ion transport gene Clca4 (chloride channel calcium activated 4), a biomarker of inflammatory bowel disease, in the colonic ECs of villin-TLR4 mice." (PMID 26755160, 2016). "CLCA4 has also been proposed as a biomarker for inflammatory bowel diseases (IBD)." (PMID 40220130, 2025).
lymph node metastasis (2 papers, 2021 to 2022). "The results of this study implicated that CLCA4 may help to discriminate potential risk of lymph node metastasis in CRC patients." (PMID 35907803, 2022). "The expression of CLCA4 was closely correlated with T stage (p=0.024), differentiation (p=0.039), and lymph node metastasis (p=0.048)." (PMID 34194494, 2021). "Simultaneously, CLCA4 expression was negatively correlated with T stage, differentiation, and lymph node metastasis." (PMID 34194494, 2021).
colitis (1 paper, 2025). Inflammation of the colon. "The human CLCA4 gene product has been proposed as modulator of EMT and biomarker in colitis and CRC." (PMID 40220130, 2025).
colorectal adenocarcinoma (1 paper, 2022). The most common type of colorectal carcinoma. "In conclusion, by integrating WGCNA and differential gene expression analysis, our study screened five important survival-related genes (SLC26A3, GUCA2A, CLCA4, CLCA1, and AQP8) and a 3-gene risk model with the potential to predict the prognosis of colorectal adenocarcinoma." (PMID 35693937, 2022).
epilepsy (1 paper, 2017). A brain disorder characterized by episodes of abnormally increased neuronal discharge resulting in transient episodes of sensory or motor neurological dysfunction, or psychic dysfunction. "Among the top ten hyper- and top ten hypo-methylated genes, a subset (i.e., GABRB1, LC34A2, CLCN6, CLCA4, CYP3A43, CYP3A4, CYP2C9) has been related to epilepsy in epidemiological, pathophysiological or clinical context (to be discussed further)." (PMID 28276448, 2017).